DUSP5 (dual specificity phosphatase 5)
Diseases named in the same sentence as DUSP5 in open-access papers (continued):
Sharing a sentence is not in itself a finding about the gene and the disease.
tumor (continued). "Likewise, DUSP5 might also affect multiple functions in several different cellular responses, including inflammation and tumor suppression." (PMID 29229953, 2017). "Thus, the DUSP5/DUSP5P1 system could be responsible for regulation of BCL2L11 leading to inhibition of apoptosis in these tumor cells." (PMID 24651368, 2014). "Mechanistically, DUSP5 inhibited ERK1/2 activation, and its tumor-suppressive effects were reversed by ERK1/2 activation." (PMID 41956999, 2026). "The present study further clarified the effects of compound 27 on the expression of DUSP5 and SCG2 in tumor cells after treatment by a combination of RNA-seq and RT-qPCR." (PMID 40473811, 2025). "Experimentally, we found that suppression of DUSP5 significantly inhibited the TGF-β signaling pathway-mediated EMT, thus impeding tumor metastasis and EGFR-TKI resistance." (PMID 38872157, 2024). "Many studies have shown that DUSP5 and NDRG1 are tumor suppressors that can effectively inhibit the proliferation and metastasis of tumor cells." (PMID 39883515, 2024). "circ_0002770 exerts its tumor-promoting role by sponging miR-331-3p, which in turn promotes expression of MAPK pathway regulators dual specificity phosphatase 5 (DUSP5) and transforming growth factor beta receptor 1 (TGFBR1)." (PMID 34638331, 2021). "Compelling evidence has demonstrated that DUSP5 and CDKN1A are key tumour suppressors in various cancers, mediating cell cycle and malignant progress." (PMID 33145887, 2021). "The DUSP5 promoter is methylated in a subset of CRC cell lines and primary tumours, particularly those with a CpG island methylator phenotype (CIMP)." (PMID 29379130, 2018). "Both DUSP5 and DUSP6/MKP-3 are amongst a subset of genes, which are often upregulated in tumours and cancer cell lines in which Ras/MAPK signalling is activated." (PMID 26791049, 2016). "Of the differentially expressed genes, IFI6, SLC39A9 and ZNF185 showed a strong correlation with tumor progression and patient survival in the OncoLnc database while roles for AKAP12 and DUSP5 in carcinogenesis and poor prognosis have previously been established for other cancer types." (PMID 32849815, 2020). "Similar to DUSP5, DUSP6 is inducible by growth and differentiating agents that activate the ERK1/2 pathway, and DUSP6 is also reported to play a tissue-specific dual tumor suppressive or pro-oncogenic role." (PMID 30866462, 2019). "Further investigation is required to determine the role of DUSP5P1 in regulating DUSP5 function, and whether DUSP5P1 expression correlates with the prognosis of or tumor remission in NB." (PMID 30866462, 2019). "Collectively, these data indicate that DUSP5 promoter methylation represents a novel marker of CIMP status in CRC but is not the predominant mechanism of DUSP5 repression in these tumours." (PMID 29379130, 2018). "However, we cannot formally exclude the possibility that DUSP5 and DUSP6 regulate tumor cell migration and invasion independently of ERK." (PMID 28910386, 2017). "In our study, DUSP5 exhibited intermediate expression relative to JUNB and CDH1, and its expression was lower in cells cultured in the 3LBNC scaffold compared to conventional plate culture, further supporting the scaffold’s ability to replicate features of the in vivo tumor microenvironment." (PMID 40558895, 2025). "In a more recent study, quercetin was shown to increase the expression of DUSP5 following binding of the Serum Response Factor (SRF) transcription factor at the DUSP5 promoter to reduce ERK1/2 activity in the nucleus and cell proliferation, resulting in a tumour-suppressive effect." (PMID 40943262, 2025). "Furthermore, DUSP5 overexpression in NS shRNA-expressing cells inhibited TNBC tumor growth, whereas DUSP5 knockdown in the ASAH1 shRNA expressing partially restored ASAH1 inhibition induced tumor growth inhibition." (PMID 38926346, 2024).
tumor (continued). "However, promoter methylation alone did not correlate with altered DUSP5 expression in CRC cell lines or primary tumours, suggesting multiple mechanisms contribute to DUSP5 downregulation in this disease." (PMID 29379130, 2018). "The reciprocal mRNA expression patterns of G9a versus DUSP5, SPRY4, PPP1R15A in datasets as well as the protein expression patterns of G9a versus Sprouty4 and GADD34 in clinical samples strengthen the correlation between G9a and these tumor suppressive genes in OCa progression." (PMID 25115793, 2014). "Our data suggest that despite a common target in the ERK MAP kinase, DUSP5 and DUSP6 play partially non-redundant roles in suppressing oncogenic KRASG12D signalling, thus retarding both tumour initiation and progression." (PMID 35418690, 2022). "Additional genes that had similar DNA and RNA frequency as DUSP5 and EI24 but no previous research on their potential role as a tumor suppressor were UBXN11, CAPN15, C6orf62, GPRIN1, KIAA2018, PCDHGA10, and PCGF1." (PMID 31484939, 2019). "Collectively, our data indicate that DUSP5 is not a major negative regulator of ERK signalling in the intestinal epithelium and has limited tumour suppressive activity in CRC." (PMID 29379130, 2018). "Thus, the authors suggested that DUSP5 does not regulate ERK1/2 signalling in the normal intestinal epithelium, while showing limited tumour suppressive activity in CRC." (PMID 40943262, 2025). "Functionally, DUSP5 depletion failed to alter ERK signalling or proliferation in CRC cell lines, and its transgenic overexpression in the mouse intestine had minimal impact on normal intestinal homeostasis or tumour development." (PMID 29379130, 2018).
cancer (59 papers, 2010 to 2026). A tumor composed of atypical neoplastic, often pleomorphic cells that invade other tissues. "Along this line, an IHC study showed that DUSP5 is downregulated in PC with respect to normal tissues and that lower DUSP5 expression is associated with cancer progression and poor prognosis, pointing to the ability of DUSP5 to act as an oncosuppressor in PC." (PMID 40943262, 2025). "DUSP5, a dual-specificity phosphatase, deactivates protein kinases and its overexpression has been linked to suppressed growth in various cancer cells." (PMID 39874307, 2025). "DUSP5 levels have been reported to be elevated in some cancers, particularly in the context of BRAF mutations." (PMID 29379130, 2018). "Recently, DUSP5 has gained increased attention in the scientific literature especially as it relates to loss or gain of expression of DUSP5 in murine models, and its associated phenotypic changes in both the immune and cancer biology systems." (PMID 26286528, 2015). "ELISA confirmed a 1.56-fold increase in DUSP5 protein concentration in mesalazine-treated cancer cells compared with controls (p < 0.001)." (PMID 41599136, 2025). "One of the first studies linking DUSP5 to cancer reported that its promoter is hypermethylated in GC tissues but not in healthy gastric mucosa." (PMID 40943262, 2025). "Consistently, BRAFV600E expression combined with Dusp5 deletion causes ERK hyperactivation and proliferative arrest, thus indicating that DUSP5 can be a novel therapeutic for cancer therapy." (PMID 34685488, 2021). "And several studies showed that suppression of DUSP5 expression correlates with cancer cell proliferation, migration, invasion and poor prognosis in different cancer types, but the relationship between DUSP5 and HPV has thus far remained undiscovered." (PMID 32849815, 2020). "For example, dual specificity phosphatase 5 (DUSP5) is required for recalibrating MAPK activation in cancer cells that have accrued B-Raf proto-oncogene, serine/threonine kinase (BRAF) mutations." (PMID 32483452, 2020). "In common with the cytoplasmic ERK-specific phosphatase DUSP6/MKP-3 (see Section 3.1.3), elevated DUSP5 expression is observed in a range of Ras or Braf mutant cancer cells where it is presumed to suppress oncogenic ERK activation." (PMID 30401534, 2019). "In another study, the expression in human cancer cells of DUSP5 and the DUSP5 pseudogene DUSP5P1 was compared, showing high ratios of DUSP5P1/DUSP5 expression in cancer cell lines, including NB cell lines, when compared to normal tissues." (PMID 30866462, 2019). "Modulation of DUSP5 expression has been shown to alter the decision of growth arrest versus proliferation of human cancer cells." (PMID 26691724, 2015). "DUSP5 could be involved in many important biological processes, including immunity, cancer, cell proliferation, and cell autophagy." (PMID 37766214, 2023). "Therefore, unveiling the precise mechanisms that govern DUSP5 expression is expected to lead to the exploration of alternative strategies for cancer treatment." (PMID 36526622, 2022). "DUSP5 is a putative tumour suppressor gene that is aberrantly expressed in several cancers." (PMID 29379130, 2018). "This latter study supports the idea that MKPs might either suppress or promote carcinogenesis depending on the oncogenic and tissue context and it will be interesting to see the results of DUSP5 ablation in other, more clinically relevant, murine models of Ras- and Braf-driven cancer." (PMID 30401534, 2019). "Dual-specificity phosphatase 5 (DUSP5) is a key regulator of the mitogen-activated protein kinase (MAPK) pathway, with established roles in various types of cancer." (PMID 41956999, 2026).
cancer (continued). "We further reveal the role of ASH1 in stimulating the MAP kinase pathway via suppressing DUSP5 in TNBC, shedding light on its diverse functions in cancer." (PMID 38926346, 2024). "In LIHC cancer cell Huh7 xenografts, knockdown of METTL3 or treatment with STM2457 resulted in decreased m6A modification and up-regulated expression of DUSP5 and SPRY2, suggesting that METTL3 suppression has a repression effect on the MAPK cascades." (PMID 38012755, 2023). "In the nucleus, DUSP5 not only inactivates ERK1/2 but also anchors ERK1/2, which was reported to paradoxically enhance cytoplasmic ERK activity in cancer via reduced ERK‐mediated RAF inhibition." (PMID 31960618, 2020). "Similar with DUSP5, FOXO1 is recently found to inactivate MAPK signaling pathway through impeding ERK1/2 phosphorylation, leading enhanced chemosensitivity of cancer cells." (PMID 29341479, 2018). "The functional role of DUSP5 and DUSP6 was investigated through their silencing in two human BRAFV600E carcinoma cell lines." (PMID 28910386, 2017). "A recently published transcriptome analysis of 496 papillary thyroid cancers confirmed that cancers with the most robust activation of MAPK signaling presented high levels of DUSP4, DUSP5 and DUSP6 mRNAs." (PMID 26691724, 2015). "On the other hand, the genes upregulated after G9a depletion include several tumor suppressor genes like dual specificity phosphatases (DUSP1, DUSP3 and DUSP5), which mediate MAP kinase dephosphorylation and are commonly repressed in many cancer cells." (PMID 25115793, 2014). "Another category of genes expressed during this time period are the dual specificity phosphatases, DUSP1, DUSP5, and DUSP7, which are involved in MAP/ERK signaling and can play roles in development or cancer." (PMID 23505351, 2013). "The DUSP5 enzyme is known to dual inactivate mitogen-activated protein kinases (MAPKs) such as extracellular signal-regulated kinases (ERK1/2) that are involved in activation of downstream targets relevant in many diseases and cancers." (PMID 40321772, 2025). "Dual-specificity phosphatase 5 (DUSP5), a protein in the serine-threonine phosphatase family, dephosphorylates ERK and is a pivotal regulator of metabolic signaling, inflammatory responses, and the progression of cancer." (PMID 40959557, 2025). "Paradoxically, DUSP5 facilitates oncogenic mutant BRAFV600E-driven cell proliferation and transformation, suggesting that DUSP5 plays an oncogenic role in BRAFV600E-driven cancers." (PMID 34685488, 2021). "Although dual-specificity phosphatase 5 (DUSP5), which inactivates extracellular signal-regulated kinase (ERK), suppresses tumors in several types of cancer, its functional roles remain largely unknown." (PMID 29229953, 2017). "However, there is relatively little evidence linking DUSP5 with human cancers." (PMID 35418690, 2022).
infection (10 papers, 2013 to 2025). The state of being infected such as from the introduction of a foreign agent such as serum, vaccine, antigenic substance or organism. "Considering the present knowledge regarding DUSP5’s role in the immune system and its induction in stress, we subjected WT and Dusp5-/- mice to acute lymphocytic choriomeningitis virus (LCMV) to determine if DUSP5 impacted T cell response to infection." (PMID 27936095, 2016). "To evaluate DUSP5’s role in T cells, we created global knockout mice, subjected them to acute infection, and monitored their T cell profile for 40 days." (PMID 27936095, 2016). "Given the high apoptotic potential for SLECs in vivo it is likely that they may be more affected by this phenomenon, driving SLEC populations down in the Dusp5-/- infection studies." (PMID 27936095, 2016). "Specifically, Dusp5-/- mice have decreased proportions of short-lived effector cells (SLECs) and increased proportions of memory precursor effector cells (MPECs) in response to infection." (PMID 27936095, 2016). "In this study we investigated the role of DUSP5 in T cell survival following infection." (PMID 27936095, 2016). "Similar, in the chicken, DUSP1, DUSP5, DUSP7, DUSP10, DUSP15, and DUSP16 were significantly downregulated in response to infection." (PMID 36683094, 2023). "From a gross perspective, Dusp5-/-(BMC) mice appeared as healthy as their WT counterparts on day 40, indicating that they were able to properly clear infection." (PMID 27936095, 2016). "Briefly, WT and Dusp5-/- mice were infected with LCMV Armstrong and blood samples were taken 8, 15, 30, and 40 days after infection." (PMID 27936095, 2016). "Infection with Singapore grouper iridovirus (SGIV), one of the most important pathogens of marine fish, could inhibit the expression of E. coioides DUSP5." (PMID 37766214, 2023). "Interestingly, infection with SARS-CoV-2 resulted in lower expression level of DUSPs, including DUSP1 and DUSP5 in infected AEC as compared to SARS-CoV-1 and MERS-CoV." (PMID 33995033, 2021). "L. rhamnosus colonization alone or combined with C. albicans infection resulted in a marginal induction of cFOS, DUSP1, DUSP5 and NFKBIA expression at early time points, but L. rhamnosus colonization before infection downregulated these genes at later stages of infection." (PMID 31413153, 2019).
neurological disorder (3 papers, 2016 to 2023). "The top-ranked hub gene, DUSP5, was enriched in neurological diseases." (PMID 27462267, 2016).
immune diseases (1 paper, 2017). "On the basis of our findings, we suggest that DUSP5 might have a beneficial effect against several immune diseases by inhibiting ERK1/2 and NF-κB signal transduction in the macrophage inflammatory response cascade." (PMID 29229953, 2017).
DUSP5 also shares sentences with these, for which no sentence is quoted: Alzheimer disease (3 papers); lung adenocarcinoma (3); Achalasia (2); cardiovascular disease (2); leukemia (2); lung cancer (2); Nephropathy (2); acute leukemia (1); anaplastic thyroid carcinoma (1); asthma (1); bacterial infections (1); brain diseases (1); brain tumors (1); Burkitt lymphoma (1); cervical intraepithelial neoplasia (1); cervicitis (1); cholangiocarcinoma (1); chronic prostatitis (1); cognitive disorder (1); colorectal tumours (1); craniosynostosis (1); diabetic encephalopathy (1); epilepsy (1); esophageal squamous cell carcinoma (1); Ewing sarcoma (1); fibrosis (1); hepatocellular carcinoma (1); Hyperglycemia (1); hypogonadotropic hypogonadism (1); hypopharyngeal cancer (1).
A further 23 diseases each share a sentence with DUSP5 in 1 paper.